MIR644A (microRNA 644a)
Synonyms: hsa-mir-644; MIR644; MIRN644; hsa-mir-644a
Gene: MicroRNA gene on chromosome 20 (34,466,325 to 34,466,418, forward strand). Ensembl gene ENSG00000207997.
Gene Ontology:
Biological process: miRNA-mediated post-transcriptional gene silencing